MMP9 (matrix metallopeptidase 9)
Diseases named in the same sentence as MMP9 in open-access papers (continued):
Sharing a sentence is not in itself a finding about the gene and the disease.
cancer (continued). "Control of MMP-9 secretion is a known anti-inflammatory effect of pioglitazone and other PPARγ ligands; they can modulate septin-2 in cancer cells preventing MMP-9 actions, and during the course of intestinal inflammations, down-modulation of PPARγ can make MMP-9 more stable." (PMID 33519451, 2020). "It was reported that SPP1 could regulate MMP-2 and MMP-9 expression and promote extracellular matrix degradation via activating αvβ-NF-κB pathway, and thus accelerate the growth, migration and invasion of cancer cells." (PMID 33240930, 2020). "High MMP9 expression is related to invasion, metastasis and angiogenesis in diverse cancers." (PMID 32905356, 2020). "In particular, decreasing expression of MMP-9 could inhibit the invasive and metastatic ability of some cancers, such as pancreatic adenocarcinoma, lung cancer, thyroid cancer, and ovarian cancer." (PMID 32382550, 2020). "AP-1 activation has been reported to regulate MMP-9 transcription and cancer invasion." (PMID 33228783, 2020). "However, iron-chelating strategies and MMP-9 small inhibitors for cancer therapy have been addressed independently." (PMID 32575507, 2020). "The expression of MMP-9 was shown to increase metastatic potentials of cancer cells." (PMID 32013255, 2020). "The expression of MMP-9 is essential for the invasive phenotype of cancer cells." (PMID 32408577, 2020). "Our observation of aspirin-treated mice harbouring cancer cells with increased MMP2 and MMP9 gene expression is intriguing and whether this has resulted from aspirin acting on the platelets or the cancer cells themselves is still to be determined." (PMID 32246008, 2020). "However, the COX-2/PGE2 pathway has been widely reported to be involved in the upregulation of MMP-9 in cancer cells and primary monocytes/macrophages." (PMID 32973660, 2020). "Combination therapies targeting LCN2, iron-level regulation, and MMP-9 activity could produce synergistic cancer cell death." (PMID 32575507, 2020). "SiRNAs suppress cancer cell metastasis (MMP-9) andproliferation (Bcl-2)." (PMID 33095554, 2020). "Accordingly, MMP-9 expression level is believed to reliably monitor cancer clinical progression." (PMID 32630531, 2020). "Besides, many crucial genes related with cancer progression, such as Cyclin D1, c-Myc, and MMP9, are modulated by Wnt/β-catenin pathway." (PMID 31949128, 2020). "We here identified a bivalent carboxylate inhibitor, previously developed as a molecule to disrupt MMP-9 homodimerization in models for cancer cell migration, as a highly specific subnanomolar inhibitor for the stable trimeric proteoform of MMP-9 (IC50 = ±0.1 nM)." (PMID 32645949, 2020). "Therefore, in this study, we also examined the role of ESM-1 in cell adhesion molecule expression, the adhesion of cancer cells to ECs, and metastasis-related factors such as MMP-9 and VEGF-A." (PMID 32466580, 2020). "These miRNAs function in OSCC mainly through modulating the expression of proteins related to cancer stem cells (augmentation of CD44, c-Myc, and Oct-4), drug resistance (upregulation of P-gp and MRP1), and EMT (increase in BMI1 and MMP9 expression and loss of E-cadherin)." (PMID 32547936, 2020). "CME was also shown to suppress cancer cell migration and invasion, and activity of MMP-9." (PMID 32328465, 2020). "In addition, the impact on the survival of cancer patients was most significant for overexpression of HMGA2, a collagen-encoding gene and MMP9." (PMID 32577156, 2020). "Thus, therapies are needed that block the function of MMP9 and additional targets in cancer cells primed by MSCs." (PMID 33119681, 2020). "The overexpression of MMP-9 in human OSCC tissues may contribute to cancer metastasis, suggesting that MMP-9 may serve as a prognostic biomarker of OSCC." (PMID 32382550, 2020).
cancer (continued). "IL-8, IL-1β, and matrix metalloproteases (MMP8 and MMP9) released from neutrophils activated endothelial cells, reduced endothelial barrier function, increased transendothelial migration and accelerated the rate of cancer cell extravasation." (PMID 32849639, 2020). "Several exosite inhibitors abrogated cancer cell migration through specific prevention of the association of pro-MMP-9 with both α4β1 integrin and CD44 without modulating the catalytic activity of MMP-9." (PMID 33373399, 2020). "Moreover, since Ezrin has been shown to modulate Matrix Metalloproteinases activity in cancer cells, we examined the effect of the two diterpenes on either MMP-9 or MMP-2 activity." (PMID 33003361, 2020). "Gene expression analysis revealed that cancer-conditioned medium upregulated the expression of CAF-associated genes including SDF-1, platelet derived growth factor α (PDGFα) and MMP9, suggesting that exposure to cancer cells induces hMSC differentiation into a CAF-resembling state." (PMID 32232008, 2020). "However, MMP-9 can also have antitumor effects; this dual behavior depends on the cancer type and/or clinical stage." (PMID 32630531, 2020). "Furthermore, CD44 can interact with MMP-9, providing the cancer cell with enhanced invasion potential." (PMID 32527062, 2020). "MMP-2 and MMP-9 have been observed in various types of human carcinoma to facilitate metastasis." (PMID 32626656, 2020). "In addition, the expression of MMP9, an important metalloproteinase in the invasion and metastasis of cancer cells, was dramatically upregulated by treatment with T-Ig." (PMID 31489935, 2019). "Besides, TIMP-2 or MMP-9 expression in cancer tissues was an independent marker for the prognosis of CRC patients by univariate and multivariate Cox regression analysis." (PMID 31293204, 2019). "In addition to this, in some cases, the inhibition of MMP-9 can be mentioned as the significant mechanism of some herbal extracts to kill cancer cells." (PMID 32377288, 2019). "MMP9 plays an important role in promoting migration and invasion of cancer cells." (PMID 31690033, 2019). "In addition, TNF-α has been found to be involved in branching morphogenesis in in vivo models, e.g., during rat mammary gland development facilitated by MMP9, suggesting that the cancer cells re-establish cellular mechanism used during early organ development." (PMID 30999696, 2019). "These immunosuppressive “N2” polarized neutrophils, which express high levels of arginase, are known to assist invasion, metastasis and angiogenesis in other cancers through the release of proteases such as neutrophil elastase and matrix metalloproteinase-9 (MMP-9)." (PMID 31824850, 2019). "Matrix metalloproteinase-9 (MMP-9) is a vital component in cancer invasion and metastasis." (PMID 31337016, 2019). "Therefore, it seems that simultaneous application of cAgNPs and cisplatin efficiently downregulated MMP-9 expression, which reduced the metastatic potential of A2780 cancer cells." (PMID 31089357, 2019). "Overexpression of MMP2 or MMP9 has been reported in various types of cancer, including OSCC." (PMID 30871117, 2019). "Additionally, IPAD data indicates a decrease in p-Mek1 (Ser217/221) in miR-29-transfected cells, an upregulator of MMP-9 activity in various cancers." (PMID 31382461, 2019). "Hence, it is possible that STAT3 activation is a common signaling intermediate that leads to the overexpression of MMP9 in malignant tumors." (PMID 31456939, 2019). "Studies have shown an overexpressed status of MMP-9 in various cancer cells." (PMID 31089357, 2019). "MMP-7 and MMP-9 may be involved in the blockage of cancer angiogenesis by cleaving plasminogen and generating angiostatin molecules." (PMID 31921634, 2019). "Expression of MMP2 and MMP9 is correlated with cancer progression and metastasis." (PMID 31106200, 2019).
cancer (continued). "In addition, knockout of TIPE2 resulted in the downregulation of CXCR-4 and MMP-9, which are involved in the invasion, migration, and metastasis of cancer cells." (PMID 31817720, 2019). "MMP-2 and MMP-9 can be activated through the urokinase plasminogen activator (uPA)/plasmin cascade, and both serve as important molecules in terms of facilitating invasion and metastasis of cancer cells." (PMID 31783709, 2019). "MMP-9 is one of the most important proteins involved in cancer cell metastasis." (PMID 31089357, 2019). "Our hypothesis was that the expression and concentration of MMP-9 and TIMP-1 are associated with TNM and histological differentiation of cancer." (PMID 31143300, 2019). "Moreover, MMP9 is one of EMT regulators that plays significant roles in cancer invasion and metastasis." (PMID 31284679, 2019). "Here we demonstrated that YKS alleviated cancer pain by suppressing the expression of MMP-9." (PMID 31239855, 2019). "The pre‐invaded GM6001‐treated monocytes formed cell–cell contact‐based junction in initial phase of invasion within the matrix (<150 μm), and then worked as a barrier for subsequent cancer cells to invade and further hampering cancer cell extravasation in addition to impaired MMP9 function." (PMID 31179226, 2019). "TIMP-1 is a natural inhibitor of MMP9 and involves in the proliferation of cancer cells." (PMID 31372176, 2019). "To verify this hypothesis, we examined the changes in the behaviors of the cancer cells when MMP-9, PDGFR-α, and PECAM-1 (CD31) were blocked in vitro and in vivo." (PMID 30483898, 2019). "MMP-2 and MMP-9, which are key factors in cancer metastasis, were affected by RBP4 overexpression." (PMID 31212896, 2019). "The present study found that MMP9 was targeted by adenine and matrine, and several studies have shown that matrine could reduce the level of MMP9 in cancer cells." (PMID 31275410, 2019). "Among the MMPs, MMP-2 and MMP-9 have been involved extensively in facilitating cancer metastasis." (PMID 31658635, 2019). "In the study of ESCC, MMP-9 is overexpression in more malignant tumors with lymph node invasion." (PMID 31824776, 2019). "MMP-9 is strongly involved in the regulation of cancer cell invasion, metastasis and angiogenesis." (PMID 31759370, 2019). "However, being a major source of MMP-9, EGF, bFGF and TGF-β, MDSCs have been heavily implicated with the EMT promotion and neoangiogenesis in several other types of cancer." (PMID 30927923, 2019). "High levels of MMP9, a gelatinase, are present in numerous cancers, including breast cancers." (PMID 30631043, 2019). "Therefore, Matrix Metalloproteinases (MMPs), in particular MMP-2 and MMP-9, are involved in cancer metastasis, and inhibitors of MMP are studied as possible antitumor tools." (PMID 31543862, 2019). "Some recent research evaluated the value of MMP-9 as biomarkers to various specific cancers." (PMID 30262739, 2018). "The MMP-2 and MMP-9, key factors in cancer metastasis, were induced by RBP4 overexpression." (PMID 29642915, 2018). "Transcripts of Versican, Vegf-c, Bcl-2, Mmp-9, Il-6 and KC were up-modulated in pituitaries isolated from transgenic mice; in in vitro studies, exogenous hCG has been shown to up-modulate transcription and expression of these molecules in cancer cells." (PMID 30410667, 2018). "Cancer biomarker represents one promising application of MMP-9 research." (PMID 30262739, 2018). "MMP-9 inhibitors are the basis for targeting MMP-9 in some cancers and other diseases, and this field may achieve breakthroughs in the future." (PMID 30262739, 2018). "Both MMP-2 and MMP-9 are vital mediators of the invasion in many cancer types." (PMID 29419740, 2018). "Our approach for simultaneously targeting MMP-9 and IL-17A paves the way toward the development of bi-specific inhibitors targeting the MMPs and pro-inflammatory cytokines for the generation of novel cancer therapy agents." (PMID 29983876, 2018).
cancer (continued). "Among the matrix metalloproteinases (MMPs), a family of zinc endopeptidases with the role on extracellular matrix protein degradation leading to the metastasis of cancer cells, specifically, the serum activities of MMP-2 and MMP-9 correlate with the invasive potential of cancer." (PMID 30115027, 2018). "The gelatinase activity of MMP-2 and MMP-9 is closely related to the invasiveness of cancer cells." (PMID 30210348, 2018). "Matrix metalloproteinases (MMPs), such as MMP-2 and MMP-9, modulate cell–cell and cell–extracellular matrix interactions via degrading various cell adhesion molecules, thereby playing vital roles in cancer cell migration, invasion, metastasis, and angiogenesis." (PMID 29867200, 2018). "Therefore, controversy still exists regarding the relationship between MMP-9 expression and clinical outcomes in various malignant tumours." (PMID 30142200, 2018). "Many studies have explored MMP-9 as a biomarker in different types of cancer." (PMID 30262739, 2018). "After 2 days of co-culture, monocytes exposed to cancer cell lines showed markedly upregulated expression of M1-associated (TNF-α, IL-1β), M2-associated (CCL13, CD206), Mreg-associated (IL-10, TGF-β), and angiogenesis associated (MMP9, VEGF) genes." (PMID 29668679, 2018). "MMP2 and MMP9 have been shown to be upregulated in angiogenic lesions, and angiogenesis is required for the growth and metastasis of invasive tumors and plays an important role in the control of cancer progression." (PMID 30154451, 2018). "Overexpression of MMP-9 has often been observed in different malignant tumors." (PMID 30262739, 2018). "IL-6-induced transcriptional factor or cytokines, such as c-Myc and vascular endothelial growth factor, initiate and promote cell growth by triggering proliferation, and MMP2 and MMP9 proteins induce cell migration, which is closely related to metastasis and invasiveness in human cancer." (PMID 30202238, 2018). "Although there were major differences between cancer cell line exposed- and mf-exposed monocytes, mRNA expression of IL-1β, MMP9, and TGM2 was shown to be significantly upregulated in monocytes following exposure to either stimuli compared to unexposed monocytes." (PMID 29668679, 2018). "MMP-9 has the potential to be clinically applied in tools in some types of cancer." (PMID 30262739, 2018). "MMP-2 and MMP-9 are commonly expressed in many malignant tumors." (PMID 30960968, 2018). "NF-κB controls the induction of MMP-9 transcription in human cancer cells." (PMID 30237403, 2018). "It is likely that the adhesion of cancer cells to the exposed submesothelial matrix is stabilized, which might promote further upregulation of MMP-9 secretion and successive invasion of cancer cells." (PMID 30544870, 2018). "High expression of MMP-9 in the CD68+/CD163+ TAMs was associated with worse OS in ER+ tumors (P <0.001) but not in ER− cancers." (PMID 30558648, 2018). "Previous studies have shown the association of FoxM1 with VEGF, MMP-9 and MMP-2 in various cancers leading to increased invasiveness and migratory ability of cancer cells causing metastasis, and targeting FoxM1 has been shown to inhibit this phenomena via down-regulation of VEGF, MMP-9 and MMP-2." (PMID 29707121, 2018). "Mechanistically, these molecules may exert their anti-metastatic effect on these cancers via a repression of matrix metalloproteinase MMP-9 activity and inhibition of cancer cell migration and invasion." (PMID 30123188, 2018). "Although significant insights on the role of MMP2, MMP3, and MMP9 in OSCCs and other cancers have been gained, the full functional/mechanistic role of DSPP-MMP20 partnering and interaction in the biology of OSCC and other cancers is just beginning to be explored." (PMID 30002682, 2018). "Then, we tested the expression level of MMP2 and MMP9, which are essential for cancer metastasis." (PMID 29642915, 2018).
cancer (continued). "In addition to matrix-degrading enzymes secreted by the cancer cells themselves, MMP-9 derived from the host microenvironments, including peritoneal mesothelial cells, appeared to contribute to the cancer cell invasion into submesothelial matrices." (PMID 30544870, 2018). "Much research has discovered the value of MMP-9 as a potential biomarker in various cancers." (PMID 30262739, 2018). "In our study, we have clearly shown that the LKB1-AMPK signalling pathway contributes to cancer cell migration and invasiveness by induction of MMP-9 expression via an Nrf2-induced pathway that is activated in response to ROS produced under conditions of glucose starvation." (PMID 29973599, 2018). "Additionally, Wnt/β-catenin pathway is also correlated with the expression and activity of MMP-2 and MMP-9, co-contributing to cancer progression." (PMID 30484490, 2018). "In non-pCR responders, the histological expression of MMP-9 of residual cancer cells is correlated with risk of relapse or death." (PMID 30241470, 2018). "EMT is cancer cells is linked to changes in the expression of EMT-transcription factors (EMT-TFs) such as SNAIL and TWIST and EMT-related genes such as E-cadherin, N-cadherin and matrix metalloprotease 9 (MMP9)." (PMID 29891854, 2018). "Exploring the utilization of MMP-9 as a cancer biomarker is a promising research area." (PMID 30262739, 2018). "In addition, expression of MMP-9, a well-recognized factor in cancer invasion and metastasis, can be stimulated by P. gingivalis and its lipopolysaccharide." (PMID 30233549, 2018). "They focused on AKT-mediated MMP-2 and MMP-9 to explain FOXC2-related cancer aggressiveness." (PMID 29801468, 2018). "Some research already explored MMP-9/NGAL complex as a potential biomarker in some cancers." (PMID 30262739, 2018). "Besides, matrix metalloproteinases (MMPs) including MMP2 and MMP9 also contribute to the invasive and metastatic phenotypes of a variety of cancer cells by degrading the extracellular matrix and other barriers." (PMID 29300772, 2018). "Several sources of evidencesuggest that the induction of TIMP-3 may inhibit MMP-2and MMP-9 activity in cancer cells." (PMID 29633599, 2018). "Therefore, it would be feasible that MMP-9 and its endogenous inhibitors (tissue inhibitors of metalloproteinases, TIMPs) are preventive and therapeutic targets for cancer metastasis." (PMID 30544870, 2018). "Similarly, androgen receptor, which is believed to play vital roles in various types of cancers, has been reported to bind directly to the promoter region of MMP-9, which upregulates MMP-9 expression and in turn promotes GC cell migration and invasion." (PMID 29795331, 2018). "MMP9 expression in implanted cancer cells has been examined by immunostaining." (PMID 29844876, 2018). "The LKB1-AMPK signalling pathway is central to an integrative molecular network that results in the induction of MMP-9 expression; this is accomplished by Nrf2 activation by a selective autophagy pathway that contributes to the survival of cells and progression of cancer." (PMID 29973599, 2018). "In addition, the reported inhibition of MDA-MB-231 and HepG2 cancer cells invasion by 6-shogaol and 6-gingerol was mediated through the modulation of MMP-9 expression and NF-κB signal pathway." (PMID 30072899, 2018). "Our data clearly shows that LKB1-AMPK signalling not only maintains energy and oxidative stress homeostasis, but could also promote cancer progression during metabolic stress conditions by MMP-9 induction." (PMID 29973599, 2018). "Thus, our overall results substantiate the possibility that MDM2 can promote the expression of MMP9 through activation of TNF-α pathway to support the invasive behavior of the cancer cells." (PMID 29748481, 2018). "In addition, the expression level of key proteins found to be over-expressed frequently existed in cancer stem cells, and anti-apoptotic protein Bcl-2, Notch-1 and MMP-9 were detected to increase in different degrees." (PMID 29914196, 2018).